HMGB1 (high mobility group box 1)
Diseases named in the same sentence as HMGB1 in open-access papers (continued):
Sharing a sentence is not in itself a finding about the gene and the disease.
clear cell carcinoma (2 papers, 2022 to 2024). "In clear cell carcinoma, HMGB1 binds to RAGE to initiate intracellular signal transduction and activate ERK, leading to increased cell growth." (PMID 38529373, 2024).
colon adenoma (2 papers, 2021 to 2023). An adenoma that arises from the colon. "AGEs, in association with RAGEs, could also induce the translocation of High Mobility Group Box-1 (HMGB1) to foster the formation of aggressive and invasive tumor phenotypes in colon adenomas." (PMID 33466626, 2021).
colorectal adenoma (2 papers, 2020 to 2022). An adenoma that arises from the colon or rectum. "Rates of positive cytoplasmic HMGB1 expression were 11.8% (8/68) in colorectal adenoma tissues and 25.2% (93/369) in CRC tissues (P < 0.01)." (PMID 33122771, 2020). "We believe that the enhancement of nuclear HMGB1 expression in colorectal adenoma and CRC lays the molecular basis for nuclear plasma translocation for the further progress of tumors in later stages of the disease." (PMID 33122771, 2020). "However, in CRC and colorectal adenoma tissue samples, high rates of nuclear HMGB1 expression (84.0% and 92.6%, respectively) and moderate cytoplasmic HMGB1 expression (25.2% and 11.8%, respectively) have been reported." (PMID 35477503, 2022). "We performed an immunohistochemical (IHC) analysis of HMGB1 expression in CRC and colorectal adenoma tissue samples obtained from a cohort of Chinese patients." (PMID 33122771, 2020). "In normal colorectal tissue, HMGB1 protein was localized in the nucleus, while some cytoplasmic localization was observed in CRC and colorectal adenoma tissue samples." (PMID 33122771, 2020). "Our study found that in normal colorectal tissue, colorectal adenoma and CRC samples, HMGB1 is generally positively expressed in the nucleus." (PMID 33122771, 2020).
coronary atherosclerosis (2 papers, 2024 to 2025). Atherosclerosis of the coronary vasculature. "Chronic HMGB1 elevation also associates with coronary atherosclerosis and frailty, and HMGB1-rich plasma from aged individuals can induce cellular senescence in vitro." (PMID 41373468, 2025). "Higher expression of HMGB1 has been observed in peripheral blood mononuclear cells (PBMCs) in patients with coronary atherosclerosis compared with patients with normal coronary arteries." (PMID 39194749, 2024). "Furthermore, the authors detected alarmin in both macrophages and VSMCs; these same cell populations were found to be positive for HMGB1 in samples of coronary atherosclerosis." (PMID 39194749, 2024).
coronary thrombosis (2 papers, 2017 to 2024). Coagulation of blood in any of the coronary vessels. "In coronary thrombosis, activated platelets has been observed to elevate HMGB1 production and incite NETs release from neutrophils." (PMID 39850900, 2024).
cutaneous vasculitis (2 papers, 2020 to 2021). Inflammation of the blood vessel wall characterized by palpable purpura. "The anti-inflammatory effects of HMGB1 blockades, including anti-HMGB1 monoclonal antibody and glycyrrhizin, have been shown in a mouse model of cutaneous vasculitis." (PMID 33807604, 2021). "We suggest that HMGB1 blockades may represent a new direction for the treatment of cutaneous vasculitis." (PMID 33133061, 2020).
cyst (2 papers, 2019 to 2023). A sac-like closed membranous structure that may be empty or contain fluid or amorphous material. "The most striking finding of this study is that the expressions of ADAMTS-13 and HMGB1 are significantly increased in the lesioned areas and the areas close to the cyst." (PMID 37863934, 2023). "The most striking finding of this study is that the expressions of ADAMTS-13 and HMGB1 were significantly increased in the lesioned areas and the areas close to the cyst." (PMID 37863934, 2023). "In addition, while plasma levels of HMGB1 and OPN correlated with the cyst sizes and total volumes, that of HA did not." (PMID 31239500, 2019).
developmental delay (2 papers, 2023 to 2024). "Notably, DECIPHER has also documented an isolated HMGB1 full-gene deletion, classified as uncertain pathogenicity, in a child with global developmental delay and language impairment (DECIPHER case number 398716), consistent with the finding in our patient." (PMID 39635340, 2024).
disc degeneration (2 papers, 2023 to 2025). "HMGB1, a ubiquitous nonhistone DNA-binding protein, is a classical inflammatory molecule and mediator involved in disc degeneration." (PMID 36945021, 2023).
endophthalmitis (2 papers, 2012 to 2022). An infectious process affecting the internal structures of the eye. "In endophthalmitis patients, increases in vitreous HMGB1 directly correlates with the duration of infection and reduction in visual acuity." (PMID 35269741, 2022). "For example, HMGB1 levels were increased in the vitreous of endophthalmitis, IR, DR, PVR/RRD, and IRDs." (PMID 35269741, 2022). "Toll-like receptors, cytokines, high-mobility group box 1 proteins, aB-crystallin and apoptosis have been studied during clinical and experimental cases of endophthalmitis." (PMID 22973073, 2012). "In a control enucleated eye due to a malignant conjunctival melanoma, HMGB1 was observed predominantly in the nuclei of retinal and choroidal cells suggesting that reduced HMGB1 concentration during endophthalmitis may reduce inflammatory induced retinal damage." (PMID 22973073, 2012).
erythroleukemia (2 papers, 2012 to 2016). Acute erythroid leukemia characterised by the presence of at least 50% erythroid precursors and at least 20% myeloblasts in the bone marrow. "Next we have explored the possible role of HMGB1/NMDAR on the differentiation process of erythroleukemia cells, induced by HMBA." (PMID 22952988, 2012).
febrile convulsions (2 papers, 2011 to 2018). "For example, serum levels of interleukin-1β (IL-1β), IL-6, and high-mobility group box 1 (HMGB1) protein in children with febrile convulsions are elevated, compared with those in children with fever alone." (PMID 30344475, 2018). "In febrile seizure patients, serum IL-1β levels were at a 4-fold increase and HMGB1 levels were at a 1.3-fold increase higher than the fever only controls (both p < 0.05)." (PMID 21989210, 2011).
Fever (2 papers, 2020 to 2025). Body temperature elevated above the normal range. "Fever is the most closely related adverse reaction to the change of HMGB1." (PMID 33473353, 2020). "HMGB1 together with IL-1β, IL-8, IL-10, and MCP-1 can serve as biomarkers to identify children with ALL and fever or SIRS who should not receive antimicrobial treatment because the origin of their fever is not due to an infectious agent." (PMID 40868835, 2025).
food allergy (2 papers, 2023 to 2024). Gastrointestinal disturbances, skin eruptions, or shock due to allergic reactions to allergens in food. "HMGB1 is the archetypal alarmin and while AGEs bind to the same receptor, there remain knowledge gaps as to whether dAGEs have identical actions as HMGB1 in its mechanisms in food allergy." (PMID 37081999, 2023).
frontotemporal dementia (2 papers, 2022 to 2024). Frontotemporal dementia (FTD) comprises a group of neurodegenerative disorders, characterized by progressive changes in behavior, executive dysfunction and language impairment, as a result of degeneration of the medial prefrontal and frontoinsular cortices. "Tau oligomers trigger cellular senescence via high mobility group box 1 (HMGB1) release and inflammatory SASP, contributing to neuropathology in AD and frontotemporal dementia." (PMID 38744709, 2024).
generalized tonic-clonic seizure (2 papers, 2020 to 2021). "Metanephrine, normetanephrine, HMGB-1, and mtDNA of partial seizure (PS) vs. generalized tonic-clonic seizure patients (GTCS)." (PMID 32581999, 2020).
glomerular disease (2 papers, 2020 to 2022). "Since NF-κB activation can increase the production of reactive oxygen species, which in turn can activate the NF-κB system, a positive feedback loop, analogous to that postulated for HMGB1, can arise, contributing to the progressive nature of the glomerulopathy." (PMID 32116790, 2020).
granulomatosis with polyangiitis (2 papers, 2014 to 2015). A small-vessel necrotizing vasculitis characterized by the association of inflammation of the vessel wall and peri- and extravascular granulomatosis. "Increased levels of HMGB1 have been found in patients with granulomatosis with polyangiitis (GPA) with active disease, especially in patients with predominantly granulomatous manifestations and in patients without renal involvement at disease onset." (PMID 24776932, 2014).
Hypoalbuminemia (2 papers, 2025 to 2026). The concentration of albumin in the blood circulation is below the lower limit of normal. "IMID exposure resulted in significant hepatocellular and neuronal damage characterized by elevated serum ALT and AST, hypoalbuminemia, hypoproteinemia, increased MDA, suppression of SOD and CAT activities, and upregulated mRNA expression of TNF-α, IL-6, and HMGB1." (PMID 41838129, 2026).
hypopharyngeal carcinoma (2 papers, 2020 to 2024). Carcinoma, predominantly squamous cell, arising from the epithelial cells of the hypopharynx. "HMGB1 can regulate TGF-β1-induced EMT of FaDu hypopharyngeal carcinoma cells through activation of RAGE." (PMID 32117622, 2020).
inclusion body myositis (2 papers, 2020 to 2022). A slowly progressive degenerative inflammatory disorder of skeletal muscles characterized by late onset weakness of specific muscles and distinctive histopathological features. "Upregulated levels of HMGB1 and RAGE have been found in the skeletal muscle of patients with inclusion body myositis." (PMID 36497194, 2022).
Intellectual disability (2 papers, 2020 to 2021). "Gene defects causing an intellectual disability are often localized to genes that regulate brain plasticity, which would be compatible with the role of HMGB1 in brain plasticity and as a candidate gene linked to intellectual disability." (PMID 32708917, 2020).
interstitial cystitis (2 papers, 2017 to 2021). A rare chronic debilitating urogenital disease characterized by urinary frequency, urgency, and pelvic pain. "MIF and/or HMGB1 are potential novel targets in the treatment of bladder pain independent of inflammation and may represent new approaches to understanding and treatment of painful bladder syndrome/interstitial cystitis." (PMID 29263120, 2017).
ischemic cardiomyopathy (2 papers, 2013 to 2018). Ischemic cardiomyopathy is a cardiomyopathy in which a weakness in the muscle of the heart due to inadequate oxygen delivery to the myocardium with coronary artery disease being the most common cause. "Differences in the condition of the host heart, i.e. acute MI versus post-MI ischemic cardiomyopathy, may also influence the impact of extracellular HMGB1 from donor cells." (PMID 24204700, 2013). "In addition, the enhancement of CXCR4 expression with HMGB1 treatment promotes the local migration to damaged tissue through the SDF-1/CXCR4 axis, which might be essential in DCM as well as ischemic cardiomyopathy." (PMID 30517097, 2018). "We have demonstrated that HMGB1 administration achieved the similar benefits to the BMC-mediated paracrine effects, including decreased fibrosis, increased vascular formation, attenuated cardiomyocyte hypertrophy, and attenuated inflammation in a rat ischemic cardiomyopathy model." (PMID 24204700, 2013).
ischemic disease (2 papers, 2015 to 2021). Lack of blood supply to an area of the body, resulting in impairment of tissue oxygenation. "The HMGB1-RAGE axis also involves in the pathophysiology of ischemic diseases." (PMID 33807604, 2021). "Several reports have demonstrated that HMGB1 plays a critical role in ischemic diseases." (PMID 26224068, 2015). "These suggest that Nrf-2-HO-1 axis may serve as a regulator for the HMGB1-RAGE axis and provide a potential therapeutic target in ischemic diseases." (PMID 33807604, 2021).
knee osteoarthritis (2 papers, 2025). "In rats with knee osteoarthritis, chrysin can alleviate neuropathic pain and reduce peripheral sensitization by inhibiting both the HMGB1-mediated activation of the RAGE/PI3K/AKT pathway and the NLRP3 inflammasome, leading to a reduction in synovitis." (PMID 40333577, 2025).
laryngeal carcinoma (2 papers, 2022). Carcinoma that arises from the laryngeal epithelium. "The mechanisms of HMGB1-RAGE signaling in M2 macrophages involved in lymphangiogenesis in laryngeal carcinoma remain poorly understood." (PMID 35280439, 2022).
lichen planus (2 papers, 2021 to 2025). A chronic, recurrent, pruritic inflammatory disorder of unknown etiology that affects the skin and mucus membranes. "While upregulation of HMGB1 was previously reported in skin lesions of lichen planus, research on DAMPs has so far been of little interest in the OLP." (PMID 41262324, 2025).
liver dysfunction (2 papers, 2021 to 2025). "Previously, we found that HMGB1 expression was highly increased in the liver of insulin receptor knockout (IR−/−) mice (a model of diabetic ketoacidosis), which developed a severe liver dysfunction associated with increased levels of HMGB1." (PMID 34360753, 2021).
malnutrition (2 papers, 2021 to 2024). Inadequate nutrition resulting from poor diet, malabsorption, or abnormal nutrient distribution. "Elevated serum HMGB1 levels are associated with renal function progression and risks of inflammation, malnutrition, and cardiovascular disease in patients with CKD." (PMID 38481996, 2024).
mucositis (2 papers, 2018 to 2023). Mucositis is inflammation and damage of the mucous membranes lining the mouth and other parts of the gastrointestinal (GI) tract. "In our study, we demonstrated the expression of HMGB1 in the cytosol of keratinized oral mucosa in 5-FU-induced mucositis specimens (data not shown)." (PMID 30274314, 2018).
Myalgia (2 papers, 2015 to 2020). "Myalgia was common and was also associated with significantly elevated serum HMGB1." (PMID 32363191, 2020).
neuritis (2 papers, 2012 to 2018). A neuropathy arising from inflammation of one or more nerves. "The NMDA/HMGB1 co-stimulus increased the number of cells bearing neuritis." (PMID 22952988, 2012).
non-Hodgkin lymphoma (2 papers, 2015 to 2021). Distinct from Hodgkin lymphoma both morphologically and biologically, non-Hodgkin lymphoma (NHL) is characterized by the absence of Reed-Sternberg cells, can occur at any age, and usually presents as a localized or generalized lymphadenopathy associated with fever and weight loss. "Indeed, in non-Hodgkin lymphoma cell lines (NHL), the combination of heat shock, γ-ray, and UVC-ray therapy induced higher amounts of calreticulin and HSP90 exposure, and HMGB-1 and ATP release than each single treatment." (PMID 25688334, 2015).
non-small cell lung adenocarcinoma (2 papers, 2024 to 2026). Type of epithelial lung cancer arising from glandular origin. "This study delved into the relationship between lipid metabolism, High Mobility Group Box 1 protein (HMGB1)–a pro-inflammatory damage-associated molecular pattern protein–and immune regulation within non-small cell lung adenocarcinoma (NSCLC)." (PMID 39100092, 2024).
obstructive sleep apnea (2 papers, 2022 to 2023). "In the soft palate of obstructive sleep apnea patients, high mobility group protein box 1 (HMGB1) was released by a large infiltration of macrophages." (PMID 36479843, 2023). "Serum level of high-mobility group box 1 protein is reportedly correlated with the severity of obstructive sleep apnea." (PMID 33461910, 2022). "We tried to evaluate the possibility of using the serum high-mobility group box 1 protein level as a biologic marker in obstructive sleep apnea patients." (PMID 33461910, 2022). "The mean apnea-hypopnea index and respiratory disturbance index values of enrolled obstructive sleep apnea patients were 50.35 ± 27.96 and 51.56 ± 28.53, respectively, and the mean serum high-mobility group box 1 protein level was 30.13 ± 19.97 ng/mL." (PMID 33461910, 2022). "High-mobility group box 1 protein may be involved in the pathogenesis of obstructive sleep apnea, and the possibility of this protein being a useful biologic marker in obstructive sleep apnea should be further evaluated." (PMID 33461910, 2022).
ovarian tumor (2 papers, 2017 to 2020). "In the library prepared from ovarian tumor tissue, 5 clones with coding sequences were identified using the HMGB1 bait (C1QA, DAG1, RPL29, RSF1, TGM2), and 6 (COMMD1, MIEN1, PCBP1, TBC1D25, ZFR, ZNF428) were identified with the HMGB2 bait." (PMID 32867128, 2020). "We hypothesised that high HMGB1 expression in ovarian tumours would predict poor patient survival." (PMID 29254158, 2017). "Of the 321 evaluable ovarian tumours stained with the HMGB1 specific monoclonal antibody, 43/321 (13%) had weak/absent staining and 278/321 (87%) had positive staining having dichotomised cases into high or low/absent expressing groups." (PMID 29254158, 2017).
parasitic infection (2 papers, 2016 to 2017). "Intracellular HMGB1 had no obvious changes in caspase inhibited mouse PMΦs without inoculation, while after parasitic infection, the nuclear HMGB1 initially decreased." (PMID 28484433, 2017).
pemphigus (2 papers, 2025). Pemphigus is a group of rare autoimmune diseases that cause blistering of the skin and mucous membranes (mouth, nose, throat, eyes, and genitals).This conditioncan occur at any age, but often strikes people in middle or older age. "It has been reported that serum HMGB1 levels are clearly increased in pemphigus patients and are significantly decreased after treatment." (PMID 40308590, 2025). "The change in HMGB1 level is closely related to disease activity and treatment response, implying that HMGB1 may be an important part of the pathological mechanism of pemphigus, and that HMGB1 may be both a biomarker of disease activity and an indicator of treatment outcome." (PMID 40102153, 2025). "In skin samples, increased cytoplasmic expression of HMGB1 and its receptor RAGE was observed in the epidermal keratinocytes of patients with pemphigus." (PMID 40308590, 2025).
Peri-Implantitis (2 papers, 2020 to 2021). An inflammatory process with loss of supporting bone in the tissues surrounding functioning DENTAL IMPLANTS. "They reported that HMGB1 expression level in GCF is indicative of the progression of peri-implantitis and may be a useful diagnostic biomarker." (PMID 32760399, 2020). "Interestingly, in the latest report, HMGB1 is involved not only in peri-implantitis but also in osseointegration." (PMID 32760399, 2020).
poisoning (2 papers, 2017). A condition or physical state produced by the ingestion, injection, inhalation of or exposure to a deleterious agent. "Furthermore, studies have shown that anti-HMGB1 antibodies and knocking out Hmgb1 in the liver reduces hepatic inflammation and liver injury in mouse models of APAP poisoning." (PMID 30873474, 2017).
primary biliary cirrhosis (2 papers, 2019 to 2021). "Previous studies have found that the level of liver HMGB1 protein was correlated with alcoholic steatohepatitis (ASH) and primary biliary cirrhosis (PBC) in patients with chronic Hepatitis C virus (HCV), as well as in chronic carbon tetrachloride (CCl4) treated mice." (PMID 34366845, 2021).
primary progressive MS (2 papers, 2015 to 2024). "Notably, a proteomic analysis of the secretome of neural progenitor cells derived from induced pluripotent stem cell lines obtained from patients with primary progressive multiple sclerosis found elevated levels of HMGB-1 associated with reduced oligodendrocyte maturation." (PMID 38965360, 2024). "HMGB1 mRNA expression levels were determined by PCR in peripheral blood mononuclear cells (PBMC) of 29 healthy controls and 57 untreated MS patients (26 with relapsing-remitting MS - RRMS, 13 with secondary progressive MS - SPMS, and 18 with primary progressive MS - PPMS)." (PMID 25879961, 2015).